PIK3CA (phosphatidylinositol-4,5-bisphosphate 3-kinase catalytic subunit alpha)
Diseases named in the same sentence as PIK3CA in open-access papers (continued):
Sharing a sentence is not in itself a finding about the gene and the disease.
liposarcoma (7 papers, 2014 to 2024). A usually painless malignant tumor that arises from adipose tissue. "Guo and colleagues also found that 22% of liposarcomas have PIK3CA mutations, and these all proved to be MRCLs." (PMID 28903344, 2017). "Further studies are needed to evaluate the potential diagnostic and therapeutic role of PIK3CA mutations and amplifications in liposarcoma." (PMID 27016421, 2016). "Despite accumulating evidence of biological role, there have been few studies reporting the frequency of PIK3CA aberration (including mutations and amplifications) for all liposarcoma subtypes." (PMID 27016421, 2016). "We investigated the epidemiologic characteristics and prognostic significance of PIK3CA mutations/amplifications in curative resected liposarcoma." (PMID 27016421, 2016). "We conducted this study to examine the frequency and prognostic impact of PIK3CA mutations and amplifications in patients with curatively resected liposarcoma." (PMID 27016421, 2016). "In this study, we evaluated the frequency of PIK3CA amplification and mutation in surgically resected liposarcoma." (PMID 27016421, 2016). "The PIK3CA mutations noted in liposarcoma (5 cases) were found in 4 myxoid liposarcomas and in 1 high grade pleomporphic liposarcoma." (PMID 25906748, 2015). "Taken together, these findings suggest that activation of the AKT/mTOR pathway in liposarcoma can occur either through activating PIK3CA gene mutations or by alternative cancer mechanisms." (PMID 24695632, 2014). "Another study reported activating PIK3CA mutations in about 14% of liposarcoma samples." (PMID 35887151, 2022). "Nine of the 105 liposarcomas (8.6%) had activating PIK3CA mutation." (PMID 27016421, 2016). "We demonstrated PIK3CA mutation and amplification in liposarcoma." (PMID 27016421, 2016). "Recent study has shown activating PIK3CA mutations were found in 14% of liposarcoma." (PMID 24695632, 2014). "We identified mutations in the PIK3CA gene in 4 of 18 human liposarcoma patients (22%)." (PMID 24695632, 2014). "Best responder was decrease of 15% in target lesions in a patient with liposarcoma harboring PIK3CA p.E545K with co-occuring NF1 p.S1420* alteration." (PMID 38126764, 2024). "In our study, by carefully assessing a large cohort of liposarcoma cases, we were able to clarify the prognostic value of PIK3CA amplification in a homogenous patient population." (PMID 27016421, 2016). "Here, we report PIK3CA aberration as an independent poor prognostic factor for curatively resected liposarcoma." (PMID 27016421, 2016). "Conversely, 2 out of 2 PIK3CA-mutant and 2 out of 3 PIK3CA-wild type liposarcoma samples demonstrated high levels of pAKT." (PMID 24695632, 2014). "Among the 150 common mutations that were evaluated across 15 oncogene and tumor suppressor genes in the screening panel, the PIK3CA gene, which encodes the p110 alpha subunit of PI3K, was the only gene that was found to be mutated in liposarcoma tissues." (PMID 24695632, 2014). "PIK3CA amplification was significantly associated with poor DFS regardless of gender, age, histology, or tumor location, as an independent prognostic factor in curatively resected liposarcoma." (PMID 27016421, 2016). "We demonstrated that PIK3CA aberration is a poor prognostic factor in liposarcoma." (PMID 27016421, 2016). "Our findings also indicate that PIK3CA inhibitor is a promising therapeutic target for liposarcoma." (PMID 27016421, 2016). "Furthermore, we also determined the prognostic impact of PIK3CA genetic aberration for liposarcoma patients." (PMID 27016421, 2016). "In our study, activating mutations in the PIK3CA gene were found in 4 out of 18 human liposarcoma samples (22%) and in none of the 19 benign lipomas or the liposarcoma cell lines tested." (PMID 24695632, 2014). "Therefore, PIK3CA may be a putative driver gene in liposarcoma, with available therapeutic agents worthwhile." (PMID 27016421, 2016).
liposarcoma (continued). "Furthermore, all 5 liposarcoma samples revealed highly expressed p4EBP1, regardless of PIK3CA mutational status." (PMID 24695632, 2014). "Western blot analysis confirmed downstream activation of AKT in both PIK3CA mutant and non-mutant liposarcoma samples." (PMID 24695632, 2014). "Western blot analysis confirmed the downstream activation of AKT in both PIK3CA mutant and non-mutant liposarcoma samples, supporting this pathway’s importance in liposarcoma tumorigenesis." (PMID 24695632, 2014). "Interestingly, in our current study, AKT and mTOR activation were also seen in PIK3CA non-mutant liposarcoma samples." (PMID 24695632, 2014). "Further investigations are required to identify these alternative mechanisms, which could include PTEN or RTK status in these PIK3CA non-mutant liposarcomas." (PMID 24695632, 2014).
metastasis (7 papers, 2016 to 2026). The spread or migration of cancer cells from one part of the body (where they first appeared) to another. "Patient #3, with MET amplification, BRCA amplification, and PIK3CA mutation, was a 51-year-old woman diagnosed with stage IV NSCLC with liver metastasis." (PMID 34249687, 2021). "Thereby, synchronous lung metastasis more frequently showed mutations in ATM, KIT, PIK3CA and SMAD4 (each with 3/5 cases as compared to 1/5 cases with metachronous liver metastases)." (PMID 27756406, 2016). "The metachronous liver metastasis had the same FGFR3 mutation but lacked the PIK3CA mutation)." (PMID 33912469, 2021). "However, PIK3CA mutations were not correlated with clinicopathological characteristics, including tumor differentiation, pathologic stage, and lymph node metastasis." (PMID 26528858, 2016). "Statistically significant relationships were present between KRAS exon 2 and mucinous morphology, PIK3CA and absence of perineural invasion, BRAF and tumor differentiation/localization, MutS homolog 3 (MSH3) and tumor diameter, and BRCA2 and absence of lymph node metastasis." (PMID 37737217, 2023).
retinoblastoma (7 papers, 2014 to 2025). A malignant tumor that originates in the nuclear layer of the retina. "Activating mutations in PIK3CA have only rarely been observed in human retinoblastoma." (PMID 28445155, 2017). "First, activating mutations in PIK3CA have been detected in human retinoblastoma." (PMID 25907958, 2015). "In vivo electroporation of constitutively active (ca)-Pik3ca, ca-Akt, or dominant-negative (dn)-Foxo1 into apoptosis prone newborn murine retina with deleted Rb/p107 eliminate Rb/E2F induced apoptosis and induce retinoblastoma emergence." (PMID 25907958, 2015). "However, the identification of JUN, PIK3CA, MAPK1 and UNC5D as hub genes in our study has thrown light on the role of inflammation, cell adhesion and cell proliferation in Rb tumors." (PMID 35359459, 2022).
salivary duct carcinoma (7 papers, 2014 to 2023). An aggressive, high grade adenocarcinoma that arises from the salivary glands. "This is, to the best of our knowledge, the largest clinical case series of AR+, PIK3CA/HRAS co-mutated salivary duct carcinoma." (PMID 37427101, 2023). "Individuals with salivary duct carcinoma can have phosphatidylinositol-4,5-bisphosphate 3-kinase catalytic subunit alpha (PIK3CA) mutations, which would sensitize the tumor to the mTOR inhibitor temsirolimus." (PMID 33859885, 2021). "Additional mutations in PIK3CA also affected particularly epithelial-myoepithelial carcinomas and salivary duct carcinomas, occurring simultaneously with HRAS mutations in almost all cases, pointing to an unknown and therapeutically relevant molecular constellation." (PMID 26053092, 2015). "After review of final histopathological diagnoses, 4 patients had salivary duct carcinoma with AR expression and HRAS/PIK3CA mutation and were included in the analysis." (PMID 37427101, 2023). "A subgroup of salivary duct carcinoma (SDC) harbor overexpression of the androgen receptor (AR), and co-occurring mutations in the HRAS- and PIK3CA-genes." (PMID 37427101, 2023). "In this study, we found that oncogenic PIK3CA protein was significantly elevated in the salivary duct carcinoma of all six patients." (PMID 24511546, 2014). "The unique treatment strategy was antiandrogen therapy in a patient with salivary duct carcinoma with HRAS and PIK3CA variation." (PMID 37976064, 2023). "The utility of PIK3CA rises to 14% (9/63) when applied to nonadenoid cystic salivary gland cancer and to 37% (6/16) for patients with salivary duct carcinoma." (PMID 35267442, 2022).
thymoma (7 papers, 2017 to 2026). A neoplasm arising from the epithelial cells of the thymus. "Beside the deregulation of the Akt/ mTOR pathway, we have identified for the first time PIK3CA mutation in a type B2/B3 thymoma, which may participate to the deregulation of the Akt-mTOR pathway, among others." (PMID 30897085, 2019). "Significant enrichment of mutated genes of the RAS and PI3K-Akt signalling pathways was reported in thymomas (AKT3, ALK, CSF1R, FGFR4, KRAS, NRAS, HRAS, PIK3CA), and their role in thymoma development was suggested." (PMID 35884448, 2022). "As previously discussed, this pathway might be activated by chromosome 19q CNV (mainly in thymomas) or by a mutation in PTEN, PIK3CA, or NF1 (in both thymomas and thymic carcinomas)." (PMID 36836670, 2023). "Among the 12 tumors, only patient 3149 (B2/ B3 thymoma) carried a non-conservative A/C transversion localized on position 56 of exon 2 of PIK3CA." (PMID 30897085, 2019). "We did not detect mutations in PIK3CA and AKT1 in type A and B3 thymomas or thymic carcinomas." (PMID 27844328, 2017).
thyroid (7 papers, 2010 to 2025). "PIK3CA amplification was associated with an overexpression of the PIK3CA protein and phosphorylation of Akt, suggesting that this alteration represents a relevant oncogenic event in thyroid tumorigenesis via the PI3K/Akt pathway." (PMID 39199391, 2024). "Indeed, the constitutive activation of MAPK and phosphatidylinositol-4,5-bisphosphate 3-kinase catalytic subunit alpha (PI3K)/v-akt murine thymoma viral oncogene homolog 1 (AKT) signaling cascades due to mutational events represents crucial molecular steps in thyroid carcinogenesis." (PMID 31540406, 2019). "In particular, PIK3CA amplifications could exert a promoting role in the initial stages of thyroid tumorigenesis, since they are also found in benign thyroid adenoma (BTA), although with low prevalence." (PMID 39199391, 2024). "Thus, overexpression of PIK3CA gene within PTC can be regarded as a potential genetic event in thyroid carcinogenesis." (PMID 20804548, 2010). "Regarding the selected genes in other CNA/UPD areas, the AKT3/PIK3CA pathway, the KRAS/RAP1B/RAP1GAP/BRAF pathway, and the VEGFC pathway have been known to participate in thyroid carcinogenesis/cancer progression." (PMID 22558328, 2012).
adenomyosis (6 papers, 2019 to 2025). The growth of endometrial tissue inside the muscular wall of the uterine corpus. "The PIK3CA mutation frequency in adenomyosis in this study was 12%, which was higher than that in the previous adenomyosis study but lower than that in the normal endometrium." (PMID 40679511, 2025). "KRAS mutations have been reported to be predominant in adenomyosis, but mutations in other cancer-associated genes, such as PIK3CA, were rare." (PMID 40679511, 2025). "We also detected these mutations in NE adjacent to adenomyotic lesions, prompting us to investigate the relevance of KRAS- and PIK3CA-mutated clones to the molecular pathogenesis of adenomyosis." (PMID 31857578, 2019). "In addition, three subjects harbored identical KRAS mutations shared between adenomyosis and uterine endometrium (subjects 2, 5, and 6), with one subject also sharing a PIK3CA mutation between these tissues." (PMID 40679511, 2025). "The MAFs of representative cancer-associated genes in adenomyosis exceeded 0.25, with KRAS and PIK3CA showing averages of 0.42 and 0.43, respectively, indicating their clonal expansion in adenomyotic lesions." (PMID 40679511, 2025). "In adenomyosis, the most frequently mutated genes included KRAS (34.1%), PIK3CA (12.2%), ARID1A (12.1%), and FBXW7 (9.8%)." (PMID 40679511, 2025). "PIK3CA was found participated in the process of gland development and epithelial cell invasiveness, which are of great importance in the pathology of adenomyosis." (PMID 32676925, 2021). "However, in this study, we focused on the genomic analysis of normal endometrium limited to the cases of adenomyosis, KRAS mutations tended to be more frequent than PIK3CA mutations." (PMID 40679511, 2025). "This implies that PIK3CA mutations may not play an important role in the development of adenomyosis." (PMID 40679511, 2025). "Obviously, further investigations are required to establish the validity of this approach, but investigation of the KRAS and PIK3CA mutation status of non-diseased uterine tissue of adenomyosis patients might greatly aid in surgical decision-making and therapeutic management." (PMID 31857578, 2019). "To investigate whether the reduced PR protein in KRAS-mutated adenomyosis samples was due to an effect of mutant KRAS on PR mRNA expression, we applied qPCR analysis to our immortalized endometrial cells overexpressing KRAS-Mut, KRAS-WT, PIK3CA-WT, or PIK3CA-Mut (please see the Source Data file)." (PMID 31857578, 2019). "The mutation frequencies per subject, regardless of sampling depths, were as follows: in adenomyosis, KRAS: 33.3%, PIK3CA: 14.3%, and ARID1A: 14.3%, and in uterine endometrium, KRAS: 66.7%, PIK3CA: 57.1%, ARHGAP35: 52.4%, PPP2R1A: 33.3%, PIK3R1: 28.6%, and FGFR2: 19.0%." (PMID 40679511, 2025).
breast angiosarcoma (6 papers, 2021 to 2025). A malignant vascular neoplasm arising from the breast. "Among primary breast angiosarcomas, mutations in PIK3CA and KMT2D are common, with PIK3CA being associated with a worse prognosis in prior studies." (PMID 41301029, 2025). "For example, in breast angiosarcoma, PIK3CA-activating mutations are observed in many tumors, which can likely serve as therapeutic targets." (PMID 34359716, 2021). "The PIK3CA/AKT/mTOR pathway is either directly or indirectly involved in the development of breast angiosarcomas." (PMID 38015377, 2023).
carcinoids (6 papers, 2015 to 2024). "Recurrent mutations in the kinase domain of PIK3CA (exon 9 and 20) have been described in 13% of typical carcinoids and 39% of atypical carcinoids by means of Sanger sequencing." (PMID 33641055, 2021). "Of note, atypical carcinoids usually carry more alterations in the MEN1 (22% vs. 6%) and PIK3CA genes (39% vs. 13%) compared to typical carcinoids." (PMID 38893145, 2024). "TERT, SDHA and RICTOR, as well as PIK3CA copy number gains were much more frequent in carcinomas than in carcinoids." (PMID 30060526, 2018). "None of the BRAF, KRAS, NRAS, or PIK3CA mutations were detected in the carcinoid tumors; moreover, none of the 56 cases exhibited MSI-high status." (PMID 26090613, 2015). "We did not detect KRAS, BRAF, or PIK3CA mutations or MSI-high in the carcinoid tumors." (PMID 26090613, 2015). "There were fewer CNAs in carcinoids than in carcinomas; however ACs showed a hybrid pattern, whereby gains of TERT, SDHA, RICTOR, PIK3CA, MYCL and SRC were found at rates similar to those in carcinomas, whereas the MEN1 loss rate mirrored that of TCs." (PMID 27873319, 2017).
carcinosarcoma (6 papers, 2014 to 2023). A malignant tumor composed of a mixture of carcinomatous and sarcomatous elements. "The SUM159 cells are mutated in the PIK3CA pathway and have carcinosarcoma features that make these cells especially refractory to treatment." (PMID 35632748, 2022). "This implies that they are important early events in the tumorigenesis of carcinosarcoma and thus could be targeted with PIK3CA/mTOR (Phosphatidylinositol-4,5-Bisphosphate 3-Kinase Catalytic Subunit Alpha /Mechanistic Target of Rapamycin Kinase) inhibitors." (PMID 31324031, 2019).
colon adenoma (6 papers, 2017 to 2025). An adenoma that arises from the colon. "One recent report of a proximal gastric adenocarcinoma in a FAP patient described a molecular pathway similar to the colonic adenoma-carcinoma sequence with somatic KRAS and PIK3CA mutations." (PMID 39776297, 2025).
cutaneous melanoma (6 papers, 2016 to 2025). A primary melanoma arising from atypical melanocytes in the skin. "These alterations appear to be particularly relevant in acral and mucosal melanomas, which are underrepresented in the TCGA’s cutaneous melanoma cohort, but show a higher prevalence of EGFR and PIK3CA mutations." (PMID 40652269, 2025). "(e.g. BRAF L597 mutation in cutaneous melanoma with MEK inhibitor, or PIK3CA mutation in solid tumors with PIK3CA inhibitors) or indicate emerging resistant subclones." (PMID 27358717, 2016).